CDX2 (caudal type homeobox 2)
Diseases named in the same sentence as CDX2 in open-access papers (continued):
Sharing a sentence is not in itself a finding about the gene and the disease.
cancer (continued). "AoV cancer subtypes were classified based on CK7, CK20, or CDX2 expression as determined by IHC staining." (PMID 38167037, 2024). "We also provide a previously unrecognized view of the potential synergisms between RUNX3 and CDX2, LHX2 and TCF3 in promoting the transcription of genes involved in cancer stem cell regulation and metastasis." (PMID 38240752, 2024). "Cancer cells also showed higher levels of the ER stress marker GRP78 and lower levels of CDX2 in the RSS2 group." (PMID 38532103, 2024). "To verify the types of fibroblasts and myofibroblasts, we employed anti-human CD31, CDX2, Cytokeratin 20, and CD45 antibodies to stain endothelial cells of blood vessels, inflammatory cells and epithelial cells or cancer cells in the tissues of samples." (PMID 36463319, 2022). "We also checked the patient outcome data using the Cistrome cancer database for TF profiles of FOXA1, HOXB13 and CDX2 in the TCGA PRAD data set54,55." (PMID 34911933, 2021). "Eight mRNA markers (MYC, VEGF, CDX2, CD133, CEA, CK19, EpCAM, and CD24) were found to be more abundant in EVs derived from cancer cell lines compared to control cell lines." (PMID 32042310, 2020). "For example, ASCL1, CDX2, IRF4, MITF, NKX2-1, PAX8 and SOX2 were pinpointed as outliers in cell lines of their corresponding cancer tissue origins." (PMID 31050342, 2019). "CDX2 is an independent prognostic biomarker in CRC, but the prognostic value is limited to stage IV cancers." (PMID 29900672, 2018). "CDX2Null/BRAFV600E expression in adult mouse intestinal epithelium led to serrated morphology tumors (including carcinomas) and BRAFV600E potently interacted with CDX2 silencing to alter gene expression." (PMID 28072391, 2017). "AGR2 expression in cancer cells induces the expression of amphiregulin (AREG) and in intestinal IEC-6 cells the transcription factor CDX2." (PMID 25111734, 2014). "Conversely, HDAC1, CCDN1, PCNA, CDX1, KRT18, CDX2 and CASP3 are all expressed at significantly lower levels in normal tissue compared to adenomatous polyp or carcinoma tissues." (PMID 25423035, 2014). "Combining CK7 and CDX2 or adding CDX2 to CK7/CK20 is useful for distinguishing subtypes, predicting disease outcomes, and impacting the clinical management of patients with AoV cancer." (PMID 38167037, 2024). "In addition, about two-thirds of these cancers belong to the CMS1 genomic category, which was only rarely observed in the non-CDX2-suppressed group." (PMID 39452477, 2024). "Groups with CDX2 suppression were compared with cancers showing no suppression regarding their clinical and genomic characteristics." (PMID 39452477, 2024). "The biopsy was performed, indicating poorly differentiated carcinoma, and the subsequent immunohistochemistry results showed PCK (+), EMA (±), CDX2 (−), CgA (−), Syn (−), CD20 (−), CD3 (−), Ki67 (+, 50%), CK8/18 (+), P63 (+), CK5/6 (+), CK7 (−), and EBER1/2‐ISH (+)." (PMID 37732493, 2023). "Patients with CDX2 expression had better overall and cancer-specific survivals than those without CDX2 expression (HR 0.735, 95% CI 0.599–0.901 and HR 0.574, 95% CI 0.431–0.764, respectively)." (PMID 35328309, 2022). "Patients with CDX2 expression had better overall and cancer-specific survival rates than those without CDX2 expression." (PMID 35328309, 2022). "In our case, the immunochemical result of CDX-2, CK20, and GCDFP-15 indicated the patient suffered from secondary PPD around the anal without underlying carcinoma according to CT scans, gastroenteroscopy, PET-CT, and any other examination methods." (PMID 34856986, 2021). "Since we previously demonstrated in cancer cell lines that MEX3A post‐transcriptionally represses the expression of caudal‐type homeobox 2 (CDX2) protein 39, a master regulator of intestinal maturation, we assessed CDX2 expression in the mutant animals." (PMID 32052574, 2020).
cancer (continued). "This is because CDX2-negative CRCs are rare, and only Japanese patients at a single cancer hospital were included in the present study." (PMID 29682204, 2018). "Out of 74 cancer specimens, 26 (35.1%) displayed a diffuse Krt7 immunoreactivity and an absence of Krt20/CDX2 expression." (PMID 29700411, 2018). "Patients with CDX2 overexpression had significantly better 3-year, 5-year, 10-year and disease-free survival outcomes in solid malignancies, regardless of the cancer type, mean age, and source region." (PMID 29179508, 2017). "Meanwhile, similar results have not been obtained for CDX2 overexpression in cancer patients with TNM I-III stage diseases." (PMID 29179508, 2017). "Cdx2 is an intestine-specific transcription factor highly expressed in the tissues of dysplasia and cancer, but is not expressed in the lung." (PMID 28608828, 2017). "Negative staining for caudal-type homeobox 2, a transcription factor indicating goblet cell differentiation, combined with absence of intramucosal carcinoma in the rectal mucosa, suggested a diagnosis of metastatic adenocarcinoma of gastric origin." (PMID 27271470, 2016). "The low-grade budding cancer, having no buds to analyze, showed the membranous β-catenin, intact E-cadherin, nuclear CDX2 and absence of ZEB2." (PMID 25528769, 2015). "Cdx2 acts as a suppressor in animal models of CRC and its expression may be decreased during tumourigenesis; however its role in human cancer is still unclear." (PMID 25972897, 2015). "Furthermore, MIXL1 expression is detected in the cancer genome atlas (TCGA) AML samples in a pattern mutually exclusive from that of HOXA9, CDX2 and HLX suggesting the existence of a core, yet distinct HOX transcriptional program." (PMID 25544748, 2014). "By immunohistochemistry, CDX2 is expressed uniformly in the majority of the colorectal and duodenal adenocarcinoma but is largely negative in the carcinomas of the genitourinary and gynecologic tracts, breast, lung, and head and neck." (PMID 24489794, 2014). "Second, data on cancer adjuvant treatments were not available, and we could not assess whether CDX2 or SATB2 expression would predict response to specific treatments." (PMID 39998677, 2025). "The IHC profile of different histological types of carcinomas allows them to be distinguished; for example, the pancreaticobiliary type expresses CK7 and mucin 5a (MUC5a), and the intestinal type expresses CK20, caudal-type homeobox 2 (CDX2) and mucin 2 (MUC2)." (PMID 36008616, 2022). "Moreover, claudin-18 (≥1%) was positively associated with cytokeratin 7 (CK7) and MUC5AC expression, showing CK7+/MUC5AC+ carcinomas the highest rate of positive cases, whereas a negative correlation was found between claudin-18 and CDX2 expression." (PMID 35925388, 2022). "Both non-atypical regions and the cancer lesion showed no nuclear expression of CDX2." (PMID 34884530, 2021). "CDX2 was identified as a negative biomarker in 14 cancer types." (PMID 34430923, 2021). "Surprisingly enough, the Fibro-BKO cells were always CK7 negative, CK20 positive and CDX2 positive and the MCF-PKO cells were always CK7 positive, CK20 negative and CDX2 negative despite being exposed to the serum of the same patient and therefore to the same circulating cancer factors." (PMID 30787346, 2019). "Moreover, Fibro-BKO cells displayed a pattern of markers expression suggestive of lower gastrointestinal tract differentiation (CK7−/CK20+/CDX2+) regardless of the cancer sera used." (PMID 30787346, 2019). "However, alterations in the CDX2 expression during cancer progression have not been examined extensively." (PMID 29682204, 2018). "Based on our pooled evidence, the CDX2 expression level may not be associated with cancer relapse, and the subgroup analysis for TNM stages and cancer types is consistent with this finding." (PMID 29179508, 2017). "No metastatic PDACs regain CDX2 expression if the primary carcinomas are negative for CDX2." (PMID 24489794, 2014).
cancer (continued). "Therefore, CDX2 expression is not completely specific for carcinoma with GI origin." (PMID 24489794, 2014). "Other investigations have suggested that the prognostic value of the lack of CDX2 expression is restricted in the CMS4 group and not seen in CMS1 cancers." (PMID 39452477, 2024). "Metastases from the cervix are immunoreactive for CK7, CEA, and p16 and are negative for ER and vimentin, and disseminations from carcinoma of the endometrium and ovary are positive for paired-box gene 8 (PAX8) and negative for CK20 and CDX2." (PMID 38674171, 2024). "On the contrary, CK20 and CDX-2 are negative markers for diagnosis of RCC, which were both positively expressed in carcinoma originating from colorectum." (PMID 28072710, 2017). "In Case 2, the neoplastic and carcinoma cells were strongly positive for MUC5AC and MUC6 but only focally positive or negative for MUC1, MUC2, CDX2, CK7, and CK20, suggesting that this immunophenotype was compatible with the gastric type." (PMID 27656307, 2016). "In Case 1, the dysplastic and carcinoma cells were strongly positive for CK7, MUC1, and MUC6 but negative or only focally positive for CK20, MUC2, CDX2, and MUC5AC." (PMID 27656307, 2016). "Notably, negative expression of the epithelial markers CDX2 and CK20 was identified in more than 80% of MMR-d cancers compared to less than 50% of MMR-p cancers." (PMID 37239344, 2023). "However, the carcinoma cells were immunopositive for estrogen and progesterone receptors and GATA3 and negative for CDX2, Hep Par 1, and MUC5AC." (PMID 25400965, 2014). "Importantly, PF failed to reinstate CDX2, alter differentiation or stemness markers, or induce cell death in PRKAB1-depleted cells, confirming target specificity of its anti-cancer effects." (PMID 41118768, 2025). "Immunohistochemistry (IHC) was nonspecific and inconsistent (positive for pancytokeratin, PAX8, and CDX2, and negative for CK7, CK20, ER, WT1, calretinin, CD31, CD34, and synaptophysin) and working diagnosis was a putative upper gastrointestinal versus mullerian cancer profile." (PMID 27171493, 2016).
adenocarcinoma (131 papers, 2007 to 2026). A common cancer characterized by the presence of malignant glandular cells. "Second, we considered pathological situations exhibiting abnormal ectopic expression of CDX2 outside the gut in the upper digestive tract, namely the esophagus and stomach, where ectopic CDX2 associates with precancerous metaplasia and adenocarcinoma." (PMID 34759958, 2021). "Our results suggest that the presence of CDX2+/GCDFP-15- PPD should prompt a careful search for primary adenocarcinoma in the lower gastrointestinal tract as the underlying adenocarcinoma determines the outcome of the patient." (PMID 32209119, 2020). "Remarkably, abnormal CDH17 expression has been described as a diagnostic marker of adenocarcinomas of the digestive system, with higher sensitivity than CDX2." (PMID 30024920, 2018). "Ki-67 was co-expressed with only a small subset of LgR5+ cells in areas which were associated with early BE (Cdx-2 positivity was observed in serial sections) (representative example of n = 41 BE and associated adenocarcinomas) and OE-33 cells." (PMID 21345220, 2011). "Diagnostic pathologists routinely use CDX2 as a marker of intestinal-type adenocarcinomas." (PMID 32245475, 2020). "Increased CDX2 expression, which is observed in approximately 90%–95% of colorectal adenocarcinomas, is considered to be a highly sensitive and specific diagnostic marker for adenocarcinomas of intestinal origin." (PMID 29682204, 2018). "Immunohistochemical staining is crucial for diagnosis, and with metastatic CRC typically expressing cytokeratin 20 (CK20) and caudal type homeobox (CDX2), it helps distinguish it from primary digital adenocarcinomas." (PMID 41953405, 2026). "A retrospective study focusing on unfavorable subgroup adenocarcinomas with gastrointestinal features (CK7+/CK20-/any CDX2 OR CK7-/CK20+/CDX2- OR CK7-/CK20-/CDX2+) reported a median overall survival (OS) of just 11.8 months." (PMID 41561743, 2025). "In patient samples, EphB2 expression correlated with CDX2 expression and was increased in gastric intestinal metaplasia and adenocarcinoma tissues compared to normal gastric mucosa." (PMID 39768557, 2024). "CDX2 has been proposed as a highly sensitive and specific marker for adenocarcinomas of intestinal origin." (PMID 38167037, 2024). "In our study, CDX2 expression loss was significantly associated with CRC in ascending colon, dMMR, partially mucinous, and poorly differentiated (high grade) adenocarcinoma." (PMID 37325467, 2023). "Histopathology of the gastric biopsy suggested adenocarcinoma, immunohistochemistry (IHC) showed CDX2 and CD 20 positivity suggesting it to be intestinal type of adenocarcinoma." (PMID 37287033, 2023). "The immunohistochemical profile of these adenocarcinomas is more complex, and, besides the loss of INI-1 expression, includes positivity for CK7, CK20 (focal) and CDX2 (focal), as well as for yolk sac markers including glypican-3, alpha fetoprotein and SALL4." (PMID 35326613, 2022). "Immunohistochemical staining was carried out to examine the expression of cytokeratin 7, cytokeratin 20, and caudal-related homeobox transcription factor 2 (CDX2) to determine the origin of the adenocarcinoma." (PMID 36532640, 2022). "We observed here that high CDX2 levels strongly upregulated the THRA promoter in all adenocarcinoma cell lines analyzed despite their different genetics and mutation statuses." (PMID 36217307, 2022). "Histopathological examination of biopsy specimens revealed an adenocarcinoma with positive immunohistochemical expressions of both CDX2 and CK20." (PMID 36574162, 2022). "In parallel, the immunohistochemical profile of these adenocarcinomas is characterized by the loss of INI-1 expression, positivity for CK7, CK20 (focal) and CDX2 (focal), as well as positivity for yolk sac markers like glypican-3, alpha fetoprotein and SALL4." (PMID 35326613, 2022). "Well-differentiated tumors also retained CDX2 expression in adenocarcinomas from Vil-Lin28b mice (n = 5)." (PMID 33755595, 2021).
adenocarcinoma (continued). "On IHC, the adenocarcinoma component stained positively for CDX2 and pancytokeratin, and the neuroendocrine component stained positively for synaptophysin and chromogranin." (PMID 34258127, 2021). "An orbital mass biopsy demonstrated an intestinal-type adenocarcinoma that tested positive for cytokeratins 7 and 20 and CDX2 on immunohistochemical staining." (PMID 34833456, 2021). "The expression of SATB2 is more specific to adenocarcinoma of the lower gastrointestinal tract origin compared to the expression of CDX2." (PMID 32867793, 2020). "Biopsy of both lesions revealed well-differentiated adenocarcinoma, and immunohistochemistry demonstrated positive expression of CDX2, substantiating its gastrointestinal origin." (PMID 30813921, 2019). "Histopathological findings indicated well-differentiated adenocarcinoma, and immunohistochemistry revealed positive expression of CDX-2, substantiating its gastrointestinal origin." (PMID 30813921, 2019). "Because of its simplicity and ease, IHC examination of CDX2 levels is widely applied in clinical studies as a sensitive marker of adenocarcinomas of intestinal origin; thus, we examined CDX2 expression in this study." (PMID 31783700, 2019). "All LAMN cases exhibited a similar immunoprofile (CK20+, CDX2+, PAX8−), while the adenocarcinoma case co-expressed CDX2 and SATB2 with negativity for CK7, CK20 and PAX8." (PMID 31771640, 2019). "Of the 36 CDX2-low CRCs, 13.9% were poorly differentiated adenocarcinoma, which is quite high when compared with only 3.6% in the CDX2-high CRCs (P = 0.02)." (PMID 30326864, 2018). "As a rather specific nuclear marker for intestinal epithelia and corresponding adenocarcinomas, CDX2—a homeobox gene coding for a transcription factor with intestine specificity—has been proposed for differential diagnostic considerations." (PMID 29721106, 2018). "Enteric adenocarcinoma is defined as adenocarcinoma with a predominant component that resembles adenocarcinoma arising in the colorectum and often shows CDX2 immunoreactivity." (PMID 28894699, 2017). "CDX2 expression has also been shown in a subset of adenocarcinomas arising from the colon, rectum, stomach, esophagus, and ovary." (PMID 27473859, 2016). "Biopsy revealed an adenocarcinoma that was immunohistologically positive for CDX2; sigmoidectomy and ureterectomy were subsequently performed." (PMID 27389415, 2016). "Here, we sought to characterize the expression profile of SOX2 and CDX2 in the sequential alterations of the esophageal mucosa towards adenocarcinoma and compare it with the well-established gastric and intestinal mucin profiles (MUC5AC, MUC6, and MUC2)." (PMID 27766003, 2016). "For this, two specimens of adenocarcinomas arising in the background of BE were assessed for the expression of CDX2, OLFM4, EPHB2, and PROM1 by qRT-PCR analysis." (PMID 25996368, 2015). "CDX2 has been shown to be expressed in intestinal development and was demonstrated in intestinal metaplasia and adenocarcinoma with the intestinal phenotype of the stomach." (PMID 22482081, 2012). "CDX2, a critical nuclear transcription factor for intestinal development, is expressed in intestinal epithelium and adenocarcinomas." (PMID 22268990, 2012). "This is notable because Cdx2 is activated during esophageal metaplastic changes, thereby facilitating, in a percentage of cases, the progression towards adenocarcinoma development." (PMID 21935353, 2011). "This is similar to a previous report in which CDX2 positivity was observed in 4 out of 4 cases of adenocarcinoma of the duodenum and 18 of 30 cases of SBA." (PMID 19935793, 2010). "Notably, only two of the tumors with dual TTF-1 and Napsin A expression that were exclusively adenocarcinomas of the upper gastrointestinal tract, were CDX2 positive." (PMID 40564811, 2025).